GCG (glucagon)
Diseases named in the same sentence as GCG in open-access papers (continued):
Sharing a sentence is not in itself a finding about the gene and the disease.
Insulin resistance (continued). "DPP-4 inhibitors can inhibit glucagon secretion by increasing endogenous GLP-1 in patients and can be used in combination with insulin to improve insulin resistance, eliminate hyperglycemic toxicity altogether, complement the mechanism, and control glucose for a long time." (PMID 36015100, 2022). "Both in DM+ and DM− groups, glucagon rose significantly after meal stimulation; this finding has already been described in patients with IFG and a positive correlation between insulin resistance and hyperglucagonemia has been observed in subjects with impaired glucose tolerance." (PMID 35563608, 2022). "MS patients have significant insulin resistance, which is not modulated by LF infection; LF+ MS subjects had high glucagon levels compared to the LF-MS group." (PMID 36482987, 2022). "However, glucagon, total-cholesterol (T-C), triglycerides (TG), LDL-cholesterol (LDL-C) and Homeostasis Model Assessment index to estimate insulin resistance (HOMA-IR) only changed in the hypercholesterolemics." (PMID 32872136, 2020). "Insulin inadequately inhibits glucagon secretion in insulin-resistant alpha cells, resulting in fasting hyperglucagonemia, which promotes fasting hepatic glucose production and IFG, especially in the setting of hepatic insulin resistance." (PMID 32774668, 2020). "Independent of insulin resistance, the levels of insulin and glucagon were mainly at fasting levels." (PMID 30908518, 2019). "Here, we tested the hypothesis that glucagon modulates hepatic GSH content, through the activation of the adenylate cyclase pathway, resulting in a state of postprandial insulin resistance." (PMID 25961284, 2015). "In contrast, hydrocortisone treatment and induction of insulin resistance increased islet numbers and area, with enhanced beta cell replication, elevated mass of beta and alpha cells, together with co-expression of GLP-1 and GIP with glucagon in islets." (PMID 24967820, 2014). "Glitazones act on insulin resistance and the incretin mimetics target the other facets of metabolic defects of T2DM, namely the abnormalities of defective insulin secretion and inappropriate glucagon secretion." (PMID 27713366, 2010). "The primary aim of this study was to evaluate whether plasma concentrations of glucagon, total GLP-1, and total GIP during an OGTT differ between children and adolescents with obesity and insulin resistance (OIR), obesity and normal insulin sensitivity (OIS), and controls with NW." (PMID 38087928, 2024). "Similarly, the IAPPO-IgA levels correlated positively with the metabolic markers glucose, glucagon, and GIP, as well as with inflammatory total IgA, CRP, and GGT, and the change in IAPPO-IgA levels correlated positively with the change in insulin resistance." (PMID 39062913, 2024). "In individuals with normal insulin sensitivity, sustained glucagon suppression was seen with lower insulin concentrations compared to individuals with insulin resistance, and glucagon is thus not suppressed to the same extent for high insulin concentrations in individuals with insulin resistance." (PMID 36752854, 2023). "Thus, in addition to ameliorating insulin resistance, HYA may modulate blood glucose levels by affecting the secretion of glucagon and incretin hormones." (PMID 37923895, 2023). "Other factors could also have an influence on the GLP-1 response, for example, insulin resistance, glucagon levels, and nonesterified fatty acid levels." (PMID 29082261, 2017). "The primary findings are: i) insulin resistance (P < 0.001) and hyperinsulinemia (P < 0.001); ii) decreased insulin disposal (P < 0.001); iii) trend for reduced GLP-1 responses at 75 g glucose; and iv) increased fasting glucagon levels (P < 0.001) in obese subjects." (PMID 26942445, 2016).
Insulin resistance (continued). "Both pancreatic and plasma levels of insulin but not glucagon were markedly elevated but glucose concentrations were relatively normal, indicating the effectiveness of markedly enhanced beta cell activity to overcome severe insulin resistance." (PMID 24967820, 2014). "Interestingly, both total and percent unmodified adiponectin were correlated with glucagon levels in controls (r = 0.999, p < 0.001), but not in cases, which is possibly a reflection of insulin resistance." (PMID 24065958, 2013). "To date, although a number of drugs have been developed to control various targets related to the pathway of insulin secretion and insulin resistance, there is no commercially available medication that effectively modulates the glucagon-signaling pathway in humans." (PMID 23226550, 2012). "Hence, the effect of GABA-mediated inhibition of glucagon secretion may be minor in inhibiting HFD-induced glucose intolerance, insulin resistance, and macrophage-related inflammation." (PMID 21966503, 2011). "Hence, in the setting of insulin resistance, it can therefore not be concluded whether a GPR119-mediated increase in GIP levels is causing the rise in glucagon after the current meal challenge." (PMID 23781322, 2013). "However, the changes of glucagon, GLP-1 and GIP hormones in viral hepatitis induced insulin resistance are not completely clear." (PMID 28085952, 2017).
type 1 diabetes (177 papers, 2009 to 2026). "Type 1 diabetes (T1D) is defined by a near-complete loss of circulating insulin and dysregulated glucagon secretion." (PMID 41026524, 2025). "A low level of insulin has also been observed in glucagon+ α-cells of insulin-deficient islets of individuals with longstanding type 1 diabetes." (PMID 41598174, 2025). "In contrast, long-term cytokine exposure caused dose-dependent suppression of glucagon secretion at 2.8 mmol/l glucose, resembling a type 1 diabetes phenotype." (PMID 40374968, 2025). "Impaired somatostatin secretion owing to loss of β- to δ-cell electrical coupling underlies defective counter-regulatory glucagon secretion in type-1 diabetes." (PMID 39313541, 2024). "As early loss of the glucagon response to hypoglycaemia is common in type 1 diabetes, the adrenaline (epinephrine) response emerges as the first-line hormonal defence against developing more severe hypoglycaemia." (PMID 38427076, 2024). "Multiple linear regression coefficients for the association of the glucagon response with ▵glucose 180 in type 1 diabetes after the BMTT." (PMID 39149119, 2024). "As a result of early loss of the glucagon response, adrenaline is the primary counter-regulatory hormone in type 1 diabetes." (PMID 38427076, 2024). "Multiple linear regression coefficients for the association of the late glucagon response with peak C-peptide in type 1 diabetes after the BMTT." (PMID 39149119, 2024). "Here, we found that GCG expression was increased in the islets of donors with type 1 diabetes, as compared with control and at-risk autoantibody-positive donors." (PMID 37558746, 2023). "It was initially thought that the alpha cell becomes dysregulated only in later stages of type 1 diabetes when loss of beta cell mass (leading to deficient insulin and unrestrained somatostatin secretion) perturbs paracrine modulation of glucagon release." (PMID 37488322, 2023). "Functional evaluation for a role of RAGE and its ligands in glucagon secretion and expression in type 1 diabetes is warranted given the associations identified here." (PMID 37558746, 2023). "The decrease in the blood glucose level after treatment with DAPA in type 1 diabetes was often associated with a reduction in the insulin dose, which leads to an increase in the glucagon level." (PMID 36650229, 2023). "Our results further confirm the contribution of metabolic factors to AN etiology; we see very robust association of AN-GReX with type 1 diabetes, the hyperglycemic hormone glucagon and various forms of insulin." (PMID 35379376, 2022). "Loss of the glucagon counter-regulatory response to hypoglycaemia occurs in many individuals with type 1 diabetes within 5 years of diagnosis and is linked, in part, to the loss of a paracrine effect of endogenous insulin on alpha cells in pancreatic islets." (PMID 32034440, 2020). "The number of hepatic lysosomes increased under conditions associated with an increase in endogenous glucagon levels, such as starvation, hypoglycemia induced by phlorizin (Becker and CornwallJr., 1971), or type 1 diabetes." (PMID 31156426, 2019). "Increased glucagon production and secretion are often associated with insulin deficiency in type 1 diabetes patients, while the conversion of adult alpha cells to beta cells has been reported following extreme beta cell loss." (PMID 25338552, 2015). "Further in vivo studies to assess the long-term relevance of taurine to the glucagon secretion and glycemic control in insulin-deficient type 1 diabetes are needed to investigate the clinical implications of our findings." (PMID 25393115, 2014). "Diabetic ketoacidosis in type 1 diabetes is triggered by insulin deficiency and subsequent excess of counteractive hormones (glucagon, catecholamines and cortisol)." (PMID 24958262, 2013).
type 1 diabetes (continued). "In type 1 diabetes, the insulin deficiency leads to low hepatic glucokinase levels resulting in decreased glucose uptake, and together with elevated glucagon levels stimulate glycogenolysis and gluconeogenesis." (PMID 23039762, 2012). "Similarly, in patients with pancreatic deficiency secondary to type 1 diabetes, the effect of intravenous glucagon on AUC of glucose over 240 min is greater than in healthy volunteers." (PMID 38579751, 2024). "The same review also suggests that the loss of glucagon response to hypoglycaemia in type 1 diabetes may be irreversible." (PMID 38392992, 2024). "However, reports have shown early loss of the glucagon response to hypoglycaemia in type 1 diabetes." (PMID 37488322, 2023). "Disruption of this mechanism may contribute, for instance, to the impaired glucagon secretion characteristic of type 1 diabetics, as loss of islet sympathetic nerves has been seen in mouse models of type 1 diabetes and in type 1 diabetic patients." (PMID 33519711, 2020). "We herein provide evidence that metabolic alterations in the α-cell model of insulinopenic diabetes may lead to a paradoxical glucagon response, which would thereby lead to glycemic instability in insulin-deficient type 1 diabetes." (PMID 25393115, 2014). "Thus, exploring the mechanisms responsible for glucose-regulated glucagon dysfunction in an insulin-deficient α-cell model may shed a light on the pathogenesis of glycemic instability in insulin-deficient type 1 diabetes." (PMID 25393115, 2014). "Isolated islets obtained from donors with type 1 diabetes have a reduced glucagon secretion during low glucose levels, but adding a somatostatin receptor inhibitor increases the glucagon secretion." (PMID 40473678, 2025). "In type 1 diabetes there are more alpha cells directly adherent to delta cells, likely increasing the alpha cells’ exposure to somatostatin which inhibits glucagon secretion." (PMID 40473678, 2025). "Long-term cytokine exposure of human islet MTs created a type 1 diabetes-like phenotype with impaired low-glucose-induced glucagon secretion." (PMID 40374968, 2025). "Several putative mechanisms behind the impaired counterregulatory glucagon secretion in type 1 diabetes have been proposed." (PMID 40374968, 2025). "The therapeutic potential of inhibition of glucagon’s action in type 1 diabetes has been extensively investigated, and a phase II trial to examine the effects of the glucagon receptor antagonist volagidemab was reported recently." (PMID 40166445, 2025). "Somatostatin inhibitors increase glucagon secretion of isolated islets from donors with type 1 diabetes." (PMID 40473678, 2025). "We analyzed pancreatic islet cells from donors with type 1 diabetes to define pathways and mechanisms responsible for altered insulin and glucagon in this disease." (PMID 41026524, 2025). "We have recently reported that the density of extra-islet glucagon-positive cells is increased almost 5-fold in pancreases from donors with type 1 diabetes with a long duration of disease." (PMID 40473678, 2025). "The blunted glucagon response to hypoglycaemia in people with type 1 diabetes is in line with earlier findings." (PMID 38376580, 2024). "The glucagon response to insulin-induced hypoglycaemia is markedly impaired in nearly all people with type 1 diabetes within approximately 5 years of disease diagnosis." (PMID 38010533, 2024). "Sensitivity analyses of the glucagon levels during the BMTT in participants with type 1 diabetes divided by peak C-peptide levels." (PMID 39149119, 2024). "We found that RAGE positively correlated with GCG expression within the control, autoantibody-positive and type 1 diabetes groups (p < 0.0001 for all)." (PMID 37558746, 2023). "Glucagon secretion in people with type 1 diabetes is present in the basal state, and responsive to the i.v. infusion of secretagogues (e.g., arginine) and amino acid ingestion." (PMID 37166980, 2023).
type 1 diabetes (continued). "Taken together, these results from microarray bioinformatics are consistent with an association between the expression of AGER, its ligands, signaling pathways and correlated genes and the expression of GCG in type 1 diabetes." (PMID 37558746, 2023). "Type 1 diabetes (T1D) is not only a disease of the β-cell, but also of the glucagon-secreting α-cell." (PMID 37152965, 2023). "The aim of this study was to assess the effect of four isocaloric meals with different macronutrient compositions on postprandial blood glucose, lipids, and glucagon in adults with type 1 diabetes (T1D)." (PMID 37513510, 2023). "When 150 micrograms (μg) of glucagon were given to patients with type 1 diabetes, peak blood glucagon levels of about 40 pM were reached, increasing their blood glucose values." (PMID 37629010, 2023). "When insulin secretion is lost in type 1 diabetes, paracrine inhibition on the α-cells is disrupted, too much glucagon is released, and glucose levels are worsened due to glycogenolysis and gluconeogenesis." (PMID 37296593, 2023). "In contrast, alpha cells from islets isolated from normoglycaemic GADA-positive donors and donors with type 1 diabetes show impaired suppression of glucagon secretion by glucose." (PMID 37488322, 2023). "In RNA microarray, RAGE (AGER) gene expression was the most important predictor of islet glucagon expression in type 1 diabetes." (PMID 37558746, 2023). "This supports an association between the expression of AGER and its correlated genes and that of glucagon secretion in the islets from type 1 diabetes donors." (PMID 37558746, 2023). "This study identified a novel association between glucagon and RAGE in human islets, including in type 1 diabetes." (PMID 37558746, 2023). "Other authors have suggested that unsuitable glucagon secretion in type 1 diabetes depends on glucagon secretion directly from the gut." (PMID 38094502, 2023). "In type 1 diabetes, the α cells have impaired glucagon secretion and an altered gene expression profile." (PMID 37558746, 2023). "Overall, these data illustrate an association between glucagon and RAGE in the α cells, with a particularly novel relationship in adolescents with type 1 diabetes." (PMID 37558746, 2023). "Leptin infusion into the ventricles of type 1 diabetes mice inhibited the expression of glucagon, consistent with the phenotype of peripheral hyperleptinemia." (PMID 37400922, 2023). "Altogether, these data further support a role for AGER and its correlated genes in modulating biological pathways and cellular components with relevance to the secretion of glucagon in type 1 diabetes." (PMID 37558746, 2023). "One unexpected outcome of this study was that we also noted the presence of MDA5 positive, but somatostatin/insulin/glucagon immunonegative cells in type 1 diabetes cases." (PMID 35957810, 2022). "There are critical gaps in our understanding of glucagon kinetics, pancreatic α cell function and intra-islet feedback network that are disrupted in type 1 diabetes." (PMID 35590248, 2022). "Further, we carried out a novel isotope dilution technique using glucagon tracers for studying glucagon kinetics in type 1 diabetes." (PMID 35590248, 2022). "A significant correlation was observed in all years between units of glucagon and persons with type 1 diabetes." (PMID 36550552, 2022). "This is important for translational research applications of evolving dual-hormone (insulin + glucagon) closed-loop artificial pancreas algorithms and their usage in type 1 diabetes." (PMID 35590248, 2022). "In type 1 diabetes (T1D), T cell mediated destruction of beta cells is accompanied by trans- and de-differentiation of beta cells to glucagon-producing alpha cells." (PMID 34542797, 2022).